TRAF6 (TNF receptor associated factor 6)
Diseases named in the same sentence as TRAF6 in open-access papers (continued):
Sharing a sentence is not in itself a finding about the gene and the disease.
tumor (continued). "Specifically, tumor-derived lactate inhibits RARγ gene transcription in macrophages through H3K18la, activating TRAF6-IL-6-STAT3 signaling to support tumor growth." (PMID 39662177, 2024). "Previous studies have demonstrated that EGCG directly binds to TRAF6, inhibiting the binding of E3 to Ubc13 and consequently reducing the E3 ligase activity of TRAF6, leading to a weakening of tumor malignancy." (PMID 38921571, 2024). "Recent research has uncovered TRAF6’s complex role in myeloid malignancies, illustrating its dual capacity as both an oncogene and a tumor suppressor." (PMID 38609495, 2024). "TRAF6 inhibition by RNA silencing or using decoy peptides has the potential to reduce tumor cell proliferation, promote apoptosis, and augment bone resorption in MM." (PMID 38169510, 2024). "It regulates inflammation and the immune response by targeting pro-inflammatory cytokines and molecules like IRAK1 and TRAF6, reducing inflammation and potentially affecting the tumor microenvironment." (PMID 39061157, 2024). "This underscores TRAF6’s tumor suppressive role and highlights the importance of a nuanced understanding of TRAF6’s diverse impacts." (PMID 38609495, 2024). "CYLD is usually considered to be a tumor suppressor gene that inhibits TRAF6 ubiquitination by binding to P62, thus modulating the entire RANKL/RANK/TRAF6 pathway." (PMID 38254792, 2024). "Utilizing short hairpin RNA (shRNA) to suppress TRAF6 expression in 5-FU resistant GC cells across both in vivo and in vitro models, we observed a marked reduction in cell proliferation and tumor growth." (PMID 39706834, 2024). "Given that previous studies have shown that NF-κB signaling pathway is crucial in tumor growth and drug resistance, we further explored the effect of the TRAF6/IRF3 axis on NF-κB-p65 in 5-FU-resistant GC cells, a key player in the NF-κB signaling pathway." (PMID 39706834, 2024). "Simultaneously, TRAF6 overexpression shows a strong correlation with tumor stage and can serve as a prognostic marker for overall survival." (PMID 38169510, 2024). "After 30 days, compared with the control group, the TRAF6 knockdown group had slower subcutaneous tumor growth, smaller volume and weight." (PMID 39706834, 2024). "It is known that MMP is involved in tumor metastasis, and TRAF6 induces MMP-9 expression by binding to BSG." (PMID 38921571, 2024). "The suppression of TRAF6 expression leads to a notable decrease in the malignant characteristics both in vitro and in vivo, underscoring the pivotal role of TRAF6 in tumor metastasis." (PMID 38921571, 2024). "We explored if TRAF6 drives tumor progression through promoting proliferation of 5-FU-resistant GC cells." (PMID 39706834, 2024). "Subsequent in vitro and in vivo experiments, including subcutaneous tumor formation in mice, demonstrated the biological roles of TRAF6 in development of 5-FU resistance in GC cells." (PMID 39706834, 2024). "The overexpression of TRAF6 promotes tumor growth and leads to poorly responses to radiotherapy and chemotherapy." (PMID 39706834, 2024). "Next, we aimed to determine if TRAF6-mediated proliferation of 5-FU-resistant GC cells and tumor growth were affected by IRF3." (PMID 39706834, 2024). "The effect of three different gRNAs targeting the gene of interest (GOI) TRAF6 on tumor cell survival was examined." (PMID 38195569, 2024). "Our results showed that the gene expression of both MyD88 and TRAF6 increased significantly in the tumor-bearing groups when compared to the control groups." (PMID 39394174, 2024). "Along this line, mir-124, miR-145 and miR-146 have been shown to repress TRAF6 protein translation and determine tumor suppressive effects on both primary and metastatic breast cancer." (PMID 36769122, 2023). "The results revealed a marked decrease in tumor volume and weight following the treatment of paclitaxel when TRAF6 expression was suppressed, but a significant increase in tumor volume and weight after PKM2 expression was upregulated." (PMID 37746908, 2023).
tumor (continued). "TRAF6 overexpression has been observed in different tumor types which can promote tumor progression by regulating various signaling pathways involved in cell proliferation and invasion." (PMID 37689738, 2023). "Although TRAF6 is involved in various axes of regulation to promote tumor chemoresistance, there has been a dearth of literature on its role in TNBC chemoresistance." (PMID 37746908, 2023). "The effect of TRAF6 inhibition for immunotherapy was investigated in Hela 1–6 tumour model and the result showed that TRAF6 inhibitors accelerated T cell‐mediated anti‐tumour immunity and blocked Treg infiltration to reduce the Treg tumour population." (PMID 36881608, 2023). "Immunohistochemistry was then performed on tumor slices to investigate the role of cinchonine in the expression of TRAF6, c‐Jun, and ATG16L2 in tumor tissue." (PMID 37484971, 2023). "TRAF6 is a bridging protein that mediates multiple signaling pathways and is overexpressed in many tumor cells, activating the AKT signaling pathway and promoting cell survival and migration." (PMID 37443080, 2023). "Our study confirmed that TRAF6 promotes tumor progression by inhibiting necroptosis mediated by the RIPK1-RIPK3-MLKL signaling pathway." (PMID 36604411, 2023). "TRAF6 was expressed at high levels in the cellular tumor zone and pseudopalisading cells around necrosis while in the microvascular proliferation zone and cellular tumor zone, IRAK1 was expressed at high levels." (PMID 37391426, 2023). "bLF specifically suppressed tumor angiogenesis through the inhibition of the NF-κB pathway by binding to TRAF6, suppressing p65 phosphorylation, the reduction of HIF-1α and its target gene expressions." (PMID 36678795, 2023). "Recently, TRAF6 has been reported to contribute to tumor angiogenesis by up-regulating HIF-1α expression." (PMID 36678795, 2023). "It has been revealed that up-regulation of miR-146a/b by FOXP3 led to inhibition of IRAK1 and TRAF6 that resulted in suppression of NF-κB and consequently tumor growth inhibition in BC." (PMID 37689738, 2023). "Next, we observed the correlation between DRAK1 and TRAF6 expression in matched tumor tissue samples." (PMID 35194034, 2022). "Taken together, these results suggest that DRAK1 acts as a tumor suppressor in TRAF6-mediated tumorigenesis of paclitaxel-resistant cells." (PMID 35194034, 2022). "The growth of cSCC cells was blocked in a TRAF6-knockdown cell line, resulting in smaller tumor sizes and delayed tumor formation." (PMID 35956111, 2022). "Intriguingly, the markedly increased expression of TRAF6 and Ki67 in HeLa/PTX tumor tissues was inhibited by DRAK1 overexpression, indicating that DRAK1 overexpression inhibits tumor progression by negatively regulating TRAF6 expression." (PMID 35194034, 2022). "A positive correlation was observed between the expression of TRAF6 and PD-L1 among these tumor tissues, further supporting the notion that TRAF6 positively regulated PD-L1 protein stability." (PMID 35361799, 2022). "TRAF6 signals are known to play critical roles in differential biological contexts including innate and adaptive immunity and tumor development." (PMID 35422093, 2022). "TGFβ type I receptor (TBRI) was shown to interact with TRAF6 through Lys63-dependent poly-ubiquitination in order to promote tumor invasion." (PMID 35874839, 2022). "Upon cellular stimuli including TLRs, IL-17R, and TNFR, TRAF6 regulates tumor cell proliferation, survival, apoptosis, and invasion through different signaling pathways." (PMID 35422093, 2022). "Studies have reported that immune checkpoint proteins affect tumor occurrence and development by regulating TRAF6, regulating toll-like receptor signal pathway and stimulating tumor immune microenvironment." (PMID 36419829, 2022). "TRAF6, a key inflammatory mediator, mediates tumor growth and metastasis and effectively reduces the migration and activation of macrophages." (PMID 36419829, 2022).
tumor (continued). "Tumor cell-derived CCL2 decreased M1-like phenotype of TAMs via ZC3H12A-TRAF6/3 signaling, whereas CD40 markedly protected the TRAF6/3 from K63-linked deubiquitination, thereby reactivating the NF-κB signaling." (PMID 35851310, 2022). "As a key factor in the various critical signaling pathway, TRAF6 overexpression was conceived to be closely correlated with tumor development and poor clinical prognosis." (PMID 34409101, 2021). "Within the tumor-free groups, there was a significant reduction in the relative transcriptional expression of Traf6 and Fbxo30 in the WFA 2 mg/kg group compared to the vehicle-treated group (p < 0.05 for both comparisons)." (PMID 33718372, 2021). "Our research suggested that the expression of TRAF6 was higher in MDSCs from tumor tissue than that in MDSCs from spleen." (PMID 33717204, 2021). "By performing an integrative cytogenetic and gene expression analysis of NSCLC and SCLC cell lines and tumours, a recurring amplification at chromosome 11p13 was identified, that only contained TNF receptor-associated factor 6 (TRAF6)." (PMID 34503110, 2021). "In lung adenocarcinoma development and progression, TRAF6 was proved to be involved in the regulation of tumor cell proliferation, invasion, metastasis, and apoptosis resistance." (PMID 34409101, 2021). "TRAF6 is abnormally highly expressed in multiple tumor tissues and modulates the malignant behavior of tumor cells." (PMID 33717204, 2021). "In the present study, we demonstrated that by mediating Akt ubiquitination and activation, regulating HIF-1α transcriptional activities, and hexokinase-2 expression, TRAF6 played an important role in the regulation of tumor glycolysis." (PMID 34409101, 2021). "After treatment with TRAF6-specific siRNA, the expression of TRAF6 in MDSCs from tumor tissue was effectively decreased." (PMID 33717204, 2021). "In this study, we found that the expression of TRAF6 in MDSCs derived from tumor tissue was significantly upregulated compared with that of MDSCs from spleen of tumor-bearing mice." (PMID 33717204, 2021). "Twenty-eight days after cell inoculation, the tumor volume in the control group was over 400 mm3, while in the TRAF6 shRNA group it was about 150 mm3 (p < 0.05), and the tumor weight is also statistically different (0.58 g vs. 0.23 g, p < 0.05)." (PMID 34409101, 2021). "The WFA 4 mg/kg group exhibited a significant reduction in relative gene expression of Fbxo30, Fbxo32, Trim63, and Traf6 compared to the tumor-free vehicle-treated group (p < 0.0001, p = 0.04, p = 0.02, p < 0.0001, respectively)." (PMID 33718372, 2021). "Downstream, K63-Ub/SQSTM1 accumulation results in the sequestration of damaged mitochondria, the CYLD K63 DUB, and the activation of the K63-Ub TRAF6-NF-κB pathway, providing metabolic, survival, inflammatory, and proliferative advantages to tumor cells." (PMID 34065348, 2021). "The results of the xenograft model confirmed that downregulation of TRAF6 in NSCLC tumor cells dramatically restrained tumor growth in vivo." (PMID 34409101, 2021). "Our data showed that knockdown of TRAF6 attenuated the ability of MDSCs to accelerate tumor progression and partly suppressed the antitumor T cell response." (PMID 33717204, 2021). "In contrast, the expression of hexokinase-2, both the total and the mitochondria fraction, was substantially decreased, implying hexokinase-2 was involved in TRAF6-mediated tumor glycolysis." (PMID 34409101, 2021). "Immunohistochemistry results demonstrated that, in the tumor tissue of the TRAF6 shRNA group, Akt phosphorylation was substantially decreased, and the expression of hexokinase-2 was also dramatically reduced, which was in accordance with the in vitro results." (PMID 34409101, 2021). "Compared with that of MDSCs from the spleens of wild-type (WT) mice or tumor-bearing (TB) mice, the expression of TRAF6 in MDSCs from tumor tissue was significantly increased." (PMID 33717204, 2021).
tumor (continued). "Our research pointed out that the expression of TRAF6 is significantly increased in MDSCs derived from the tumor tissue of tumor-bearing mice." (PMID 33717204, 2021). "Our studies demonstrated that TRAF6 had an important role in the regulation of tumor glycolysis and was a promising therapeutic target for tumor management." (PMID 34409101, 2021). "In one cohort, TRAF6 expression was higher in the tumor than surrounding tissues in 59.6% of the patients and was inversely related to chemo-sensitivity, but unrelated to cancer stages or overall survival." (PMID 33015045, 2020). "Through this signalling pathway, the tumorigenic ability of TRAF6 can be alleviated by crosstalking a tumor suppressive gene TXNIP, leading to a decline in tumogenesis." (PMID 31578830, 2020). "Multiple studies have found that TRAF6 expression is increased in a variety of tumor tissues compared to normal tissues." (PMID 33294443, 2020). "Co‐expression of miR‐605‐3p and TRAF6 largely reversed the tumour‐suppressive effects of miR‐605‐3p up‐regulation alone, which suggests that miR‐605‐3p inhibits the malignant behaviour of HCC cells by suppressing TRAF6 expression." (PMID 32436333, 2020). "Our data indicate that TRAF6-HIF-1α interaction contributes to tumor growth, primarily through modulation of angiogenesis, likely through stabilization of HIF-1α proteins levels in tumor cells." (PMID 33142239, 2020). "Mice with restricted deletion of TRAF6 in Tregs were resistant to implanted tumours and displayed enhanced antitumour immunity because Foxp3 underwent K63-linked ubiquitination at lysine 262 as mediated by TRAF6." (PMID 32680511, 2020). "The histological analysis of TRAF6-KD tumors showed increased apoptosis (cleaved-caspase-3+), but also increased tumor cell proliferation as determined by Ki67 staining, when compared to Mock tumors." (PMID 33142239, 2020). "The abnormal expression of TRAF6 is closely related to carcinogenesis by participating in the regulation of tumor cell apoptosis, growth, and invasion through different signaling pathways." (PMID 33138076, 2020). "We identified TRAF6 as a potential binding partner of HIF-1α in MC-38 tumor cells under hypoxia and confirmed that TRAF6 physically interacts with HIF-1α as visualized by proximity ligation assay." (PMID 33142239, 2020). "This review summarizes and analyzes the role of TRAF6 in tumorigenesis and tumor development in combination with the current research on TRAF6 and tumors." (PMID 32905356, 2020). "In this review, we summarize the advanced research of the role of TRAF6 in tumorigenesis and tumor development, as well as provide tumor therapeutic strategies targeting TRAF6." (PMID 32905356, 2020). "Evidences also confirmed that miR-146b-5p is tumor suppressor by inhibiting the TRAF6/p-Akt signaling pathway in vitro and in vivo." (PMID 32905356, 2020). "To exclude that TRAF6-KD tumor cells have a general problem to proliferate in vivo, we intravenously injected these cells and followed metastasis to the lungs." (PMID 33142239, 2020). "Studies suggest that TRAF6, IRAK1 andEGFR, a protein associated with tumour progression andmetastasis, are targets for mir146a-5p." (PMID 32142098, 2020). "We also tested the cell proliferation via nude mice xenograft experiment, we observed nude mice injected the cells expressing TXNIP sh4 had larger tumor size than that of cells expressing TXNIP sh4/TRAF6 sh34." (PMID 31578830, 2020). "In keeping with the notion that TRAF6 is necessary for Treg‐mediated immune restrain, the severely stunted tumor progression in Traf6fl/flFoxp3Cre+ mice coincided with a markedly enhanced anti‐tumor response." (PMID 30886050, 2019). "Genetic ablation of TRAF6 attenuates skeletal muscle wasting in response to starvation, denervation, and tumor growth potentially through inhibition inflammatory signaling pathways and proteolytic systems." (PMID 31817027, 2019).
tumor (continued). "Cezanne, a newly identified member of the A20 family of deubiquitinases, can act as a potential tumor suppressor via NF-κB activity by deconjugating K63-polyubiquitin chains from TRAF6 and RIP." (PMID 31185898, 2019). "Additional exploration of the relative importance of this newly uncovered role for TRAF6 and its other potential contributions to the tumor–immune cell interface, however, will be needed." (PMID 30886050, 2019). "~4–10% of cSCC patients had distant metastasis, and therefore, we also tested the effect of TRAF6 on tumor cell migration." (PMID 29463844, 2018). "Taken together, both tumor suppressive and oncogenic roles of TRAF6 have been reported in human liver cancer and prostate cancer." (PMID 30294322, 2018). "In agreement with the in vitro data, silencing TRAF6 expression significantly blocked cSCC cell growth, thus resulting in smaller tumor sizes and delayed tumor formation." (PMID 29463844, 2018). "In tumor tissues, the expression levels of TRAF6, p-Akt, p-mTOR and p-p65 proteins were decreased in the TRAF6 shRNA groups compared with the control groups." (PMID 29703234, 2018). "TRAF6 levels were found to be increased significantly in tumors compared with non-tumor oral tissues." (PMID 29703234, 2018). "The tumor volume and tumor weight were reduced in the TRAF6 shRNA groups compared with the control groups." (PMID 29703234, 2018). "Intriguingly, several TRAF6-dependent tumor suppressive pathways have also been described for human cancers in the literature." (PMID 30294322, 2018). "Remarkably, TNF receptor associated factor 6 (TRAF6) was confirmed as a direct target of miR-146b-5p in HCC and miR-146b-5p exerted the tumor suppression roles through inhibiting the phosphorylation of Akt mediated by TRAF6." (PMID 28404923, 2017). "Tumor necrosis receptor factor 6 (TRAF6) is a potent inducer of mitophagy, and TRAF6 deletion can prevent cancer-induced muscle mass in tumor-bearing mice." (PMID 28785374, 2017). "Inhibition of TRAF6 suppresses NF-κB activation, and subsequent anchorage-independent growth and tumor formation." (PMID 26769849, 2016). "In vivo analyses also validated that FOXP3-mediated induction of miR-146a resulted in the downregulation of IRAK1 and TRAF6 and subsequently inhibited NF-κB activation, thus leading to tumor suppression in breast cancer cells." (PMID 26682271, 2015). "In these same cells, IRAK1 knockdown combined with TRAF6 knockdown by siRNA increased invasion and tumor volume, but IRAK1 knockdown alone had few effects." (PMID 26527316, 2015). "Ultimately, FOXP3-induced miR-146a/b inhibited NF-κB activation by repressing IRAK1 and TRAF6, which led to tumor suppression and apoptosis during tumor initiation in breast and prostate epithelial cells." (PMID 26682271, 2015). "It has been indicated that tumor necrosis factor receptor-associated factor-6 (TRAF6) will upregulate the expression of hypoxia-inducible factor-1α (HIF-1α) and promote tumor angiogenesis." (PMID 25089269, 2014). "TRAF6 also upregulates the expression of hypoxia-inducible factor 1α (HIF-1α) to promote tumor angiogenesis." (PMID 25340740, 2014). "The molecular mechanisms through which miR-146a contributes to tumor development are unclear but they seem to be related to the ability of this miRNA to target some mRNAs, such as TRAF6, IRAK1, CXCR4, NF-κB and EGFR." (PMID 24376808, 2013). "CYLD, a tumor suppressor and a target gene of NF-κB, negatively regulates NF-κB and JNK activation by removing K63-linked polyubiquitin chains from TRAF2 and TRAF6 as well as several other signaling proteins." (PMID 23758787, 2013). "In paclitaxel-resistant cells, DRAK1 protein is degraded by the SPOP through K48-linked polyubiquitination-mediated proteasomal degradation, leading to an increase in TRAF6 levels and subsequent TRAF6-mediated NF-κB activation, which promotes tumor progression." (PMID 40521202, 2025).